XRCC1 (X-ray repair cross complementing 1)
Diseases named in the same sentence as XRCC1 in open-access papers (continued):
Sharing a sentence is not in itself a finding about the gene and the disease.
tumor (95 papers, 2005 to 2025). "By closely examining the relationship between XRCC1 and immune cell infiltration, we will seek to elucidate the precise mechanism underlying XRCC1 in regulating tumor immune response." (PMID 38217545, 2024). "Overall, XRCC1-mediated infiltration of various immune cells in the tumor microenvironment is likely to be closely associated with tumor prognosis." (PMID 38217545, 2024). "The study also investigated the association between XRCC1 gene expression levels and two significant biomarkers related to immunotherapy response: tumor mutational burden (TMB) and microsatellite instability (MSI)." (PMID 38217545, 2024). "YY1 activates the expression of breast cancer-associated gene 1 (BRCA1) and X-ray repair cross-complementing 1 (XRCC1), which repair DNA damage caused by chemotherapy drugs, thereby protecting tumor cells from apoptosis." (PMID 37444616, 2023). "XRCC1 is significantly correlated with the number of tumors, tumor size, and location, and is also an independent risk factor for the poor prognosis of HCC." (PMID 33868991, 2021). "We have previously shown that a BER deficiency, brought about by downregulation of XRCC1 by siRNA, induces wide-ranging gene-expression changes in cellular metabolism that are comparable to changes found in tumours." (PMID 32228693, 2020). "Previous works have demonstrated that XRCC1 is associated with tumor resistance to chemotherapy and radiotherapy, carcinogenesis, and tumor progression." (PMID 32426369, 2020). "DNA excision repair protein 1 (ERCC-1), ERCC-2 gene polymorphisms, X-ray repair cross-complementing protein 1 (XRCC-1) polymorphisms seem to be associated with tumor response." (PMID 32197436, 2020). "This is supported by clinical data suggesting that EOC tumours overexpressing XRCC1 and were more likely to be high grade serous cancer, demonstrate platinum resistance, increased risk of death and increased risk of tumour progression." (PMID 29925418, 2018). "Altogether, these data show that XRCC1 downregulation is associated with the emergence of CAF markers in human tumour stroma samples and fully confirm the observations we made in vitro." (PMID 29568385, 2018). "XRCC1 deficiency in the tumour stroma is likely, as demonstrated by our study, to act in synergy with ROS in the microenvironment and aggravate the accumulation of DNA breaks in order to amplify the pro-inflammatory response." (PMID 29568385, 2018). "Several markers, including tumor stage, tobacco smoking, ki-67 expression, cyfra and XRCC1 (X-ray repair cross-complementing protein 1) polymorphism have been reported as prognostic indicators of outcomes in NSCLC patients." (PMID 29163831, 2017). "We conducted subgroup analyses by ethnicity, tumor site, publication year, and genotyping method to estimate the relationship between XRCC1 Arg280His variant genotypes and the risk of NHC." (PMID 24086310, 2013). "The contributions of the XPD and XRCC1 allelic variants to OS are tumor site- and/or stage-dependent." (PMID 23894404, 2013). "Our results showed that the XPD and XRCC1 allelic variants were tumor site- and/or stage-dependently associated with OS for CRC patients receiving 5-FU-based chemotherapy." (PMID 23894404, 2013). "In addition, we found a mutation rate of XRCC1 of 1.8% in all tumor patients and a copy number deletion of XRCC1 in all DLBC cases." (PMID 38217545, 2024). "For instance, while polymorphic variants in the GSTP1 gene have been associated with the metabolism of pesticides and with the development of neoplasms, polymorphisms in the XRCC1 gene have been linked to an elevated risk of DNA damage caused by pesticide exposure." (PMID 38673753, 2024). "All this evidence suggests that XRCC1 is closely associated with tumor resistance." (PMID 38217545, 2024). "The XRCC1 Arg194Trp gene polymorphism is associated with tumor stage (p < 0.05)." (PMID 39445528, 2024).
tumor (continued). "Polymorphisms in the XRCC1 gene are associated with a decrease in the ability of the protein product of this gene to repair DNA, an increase in the number of gene mutations, and the risk of tumor formation." (PMID 37368581, 2023). "Similarly, XRCC1 positive expression was positively associated with large tumor size (>3 cm), lymph node metastasis, invasion, late TNM stages (III + IV), only receiving biopsy in AC (all P < 0.05)." (PMID 32426369, 2020). "Moreover, expression of XRCC1 has been shown to be decreased in various different tumours, with lower XRCC1 levels associated with higher proliferation and shorter overall survival." (PMID 32228693, 2020). "Despite previous publications indicating a loss in XRCC1 to be an important indicator for TNBC, XRCC1 transcript expression levels were significantly higher in primary tumor samples than in normal tissues with a p value of 1.6 x 10−12 (Primary tumor to Normal)." (PMID 31596905, 2019). "Additionally, a clinical study has shown that XRCC1 280 is significantly associated with the number of tumors, tumor size, and tumor location and is an independent risk factor for poor prognosis in patients with HCC." (PMID 30408066, 2018). "It has also been demonstrated thatXRCC1 Arg399Gln is correlated with the incidence of theabove-mentioned tumours and that allele Gln increases the risk of these tumours.Similarly, the present study also found that XRCC1 Arg399Glnpolymorphism is associated with the risk of PACG." (PMID 28396513, 2017). "Many studies have indicated that XRCC1 expression is up-regulated in tumor progression and might be a risk factor for tumor progression." (PMID 29312615, 2017). "Additionally, the biological mechanisms of IRF9 and XRCC1 underlying tumor suppression, prevention, and inflammation were carefully addressed." (PMID 27421136, 2016). "The relationship between HNC susceptibility and variant genotypes of XRCC1 might be affected by the tumor sites." (PMID 24086310, 2013). "This was also supported by the association of the XRCC1-399 Gln allele with higher grade tumours." (PMID 16280050, 2005). "Non-synonymous mutations of XRCC1 gene cause amino acid sequence changes that affect protein function and DNA repair ability, and may affect the interaction with other DNA repair proteins, leading to increased risk of tumor development." (PMID 34918657, 2021). "Thus, our results may shed light on the value of the XPD Ly751Gln and XRCC1 Arg399Gln allelic variants as prognostic markers for CRC of various tumor sites and stages." (PMID 23894404, 2013). "This, in turn, triggers lactylation-induced nuclear translocation of XRCC1, enhancing DNA repair and potentially contributing to tumor resistance to radiotherapy and chemotherapy." (PMID 39979245, 2025). "Lactylation of XRCC1 altered its surface charge, increasing its affinity for importin α and leading to nuclear ectopia, which further promoted DNA repair and tumor progression." (PMID 39925738, 2025). "XRCC1, XRCC3, ERCC1, and ERCC2 encode proteins crucial for the repair of DNA damage induced by ionizing radiation, directly affecting tumor cell radiosensitivity." (PMID 41463244, 2025). "In our analysis, we investigated the differences in XRCC1 protein expression and phosphorylation between primary tumor tissues and normal tissues." (PMID 38217545, 2024). "Further exploration of the genetic alteration status of XRCC1 in different tumor samples within the TCGA cohort showed distinct patterns." (PMID 38217545, 2024). "The study utilized the TIMER and XCELL datasets to investigate the correlation between XRCC1 expression and immune infiltration in multiple tumor tissues." (PMID 38217545, 2024).
tumor (continued). "To assess the expression of XRCC1 in tumor tissues compared to their matched adjacent tissues, we performed the Wilcoxon signed rank sum test." (PMID 38217545, 2024). "To examine the protein expression of XRCC1, we utilized the Clinical Proteomic Tumor Analysis Consortium (CPTAC) database." (PMID 38217545, 2024). "XRCC1, a gene closely related to DNA damage repair, plays an important role in tumor resistance to radiotherapy and chemotherapy." (PMID 38217545, 2024). "The positive correlation between XRCC1 expression and immune cell infiltration suggests its involvement in the tumor immune microenvironment." (PMID 38217545, 2024). "Firstly, we analyzed the expression status of XRCC1 in various tumor tissues and paired normal tissues." (PMID 38217545, 2024). "In this study, by analyzing the differences in the expression of SDF-1ɑ and XRCC1 between tumor tissues and normal tissues, we found that the expression of SDF-1ɑ was increased in normal tissues and that the expression of XRCC1 was increased in RCC tissues." (PMID 38337001, 2024). "We further validated our findings by analyzing the expression of XRCC1 in normal samples from the Genotype-Tissue Expression (GTEx) database and matched adjacent tumor tissues." (PMID 38217545, 2024). "Among them, XRCC1–6 is a recognized member of the XRCC family, highly expressed in various tumour tissues and exhibiting multiple mutations in pan-cancer." (PMID 37679817, 2023). "As expected, patients whose tumours had low XRCC1/low Mre11 co-expression (22.8%) had better progression free survival (p = 0.014) and overall survival (p = 0.005) compared to tumours that had high XRCC1/high Mre11 co-expression (48.7%)." (PMID 35853939, 2022). "circFLNA overexpression has been found to promote tumor growth, inhibit miR-486-3p expression and promote the expressions of XRCC1 and CYP1A1, however, miR-486-3p mimic led to the opposite effect of overexpressed circFLNA." (PMID 33500536, 2022). "XRCC1 rs25487 affects the activity of DNA repair enzymes and thus the sensitivity of tumor cells to platinum-based drugs." (PMID 36497451, 2022). "It is clear that AIL can not only induce DNA damage but also inhibit DNA repair by downregulating P23 expression, which in turn inhibits the DNA repair capability of XRCC1, thereby exerting a tumor-suppressing effect on GC." (PMID 34345209, 2021). "Patients whose tumours had high LIG1/high XRCC1 had worse PFS after platinum-based chemotherapy compared to patients whose tumours had low LIG1/low XRCC1 co-expression." (PMID 34373746, 2021). "The results demonstrated that XRCC1 expression in GBC tissues was significantly higher than adjacent non-tumor tissues both in mRNA and protein levels." (PMID 32426369, 2020). "The result showed that the XRCC1 expression levels were significantly decreased in tumor tissues compared with the corresponding adjacent normal tissues." (PMID 32185826, 2020). "The analysis indicated a significantly higher expression level of IRF9 and XRCC1 in PsP (diagnosis for pseudoprogression) cases than those for the true tumor progression (TTP) patients in both private and TCGA/TCIA data." (PMID 31795520, 2019). "XRCC1 transcript expression levels were higher in tumor samples than in normal tissues, and in Luminal and TNBC subtypes compared with normal tissue." (PMID 31596905, 2019). "This analysis suggested that the proteomic profile of XRCC1 KD cells was reminiscent of that usually observed in CAFs and tumour cells, indicating that fibroblasts experience major phenotypical rearrangements in response to persistent DNA damage." (PMID 29568385, 2018). "Both germline and tumor-associated variants of genes encoding SSB repair proteins (e.g., XRCC1, APE1, and Polymerase beta) have been identified in humans, suggesting SSB repair as a tumor suppressor mechanism." (PMID 30110897, 2018). "Comparison between tumour and control samples showed a substantial downregulation of XRCC1 in the tumour stroma." (PMID 29568385, 2018).
tumor (continued). "Immunohistochemical staining was used with TMA slides to evaluate XRCC1 expression in ccRCC and paired adjacent non-tumor tissues." (PMID 29312615, 2017). "Poorly differentiated tumours were associated with increased MPG (p=0.033) and XRCC1 (p=0.042) expression." (PMID 28903334, 2017). "BZA treatment also significantly reversed chemo and radioresistance in tumor cells by downregulating XRCC-1, ERCC-1 and survivin." (PMID 28978005, 2017). "Our data demonstrated that XRCC1 expression was dramatically decreased in ccRCC tissues compared with that in normal renal tissues and paired adjacent non-tumor tissues." (PMID 29312615, 2017). "Taken together, the expression of XRCC1 expression was reduced in ccRCC tissues compared the expression in non-tumor tissues." (PMID 29312615, 2017). "Our univariate analysis showed that XRCC1, tumor diameter, pT status and TNM stage were correlated with the overall and disease-specific survival of ccRCC patients." (PMID 29312615, 2017). "Next, we assessed protein expression levels by immunohistochemistry for MLH1, MPG, FEN1, Polβ and XRCC1 in tumour vs. healthy tissue of this patient cohort." (PMID 28903334, 2017). "The PI3K/Akt pathway has also been reported to regulate the basal expression of XRCC1 in human tumor cells." (PMID 29117108, 2017). "We analyzed XRCC1 expression, age, tumor diameter, pT status and TNM stage by univariate and multivariate Cox regression analysis." (PMID 29312615, 2017). "There are some studies however, which have directly addressed the expression levels of XRCC1 in normal versus tumour tissue." (PMID 25800737, 2015). "Our group has demonstrated the possibility of JWA participating in tailored therapy of tumor for its novel function as regulator of XRCC1." (PMID 25925371, 2015). "XRCC1 expression levels were significantly enhanced in tumor samples and were correlated with all clinical and histopathological data." (PMID 25268610, 2014). "ATM +/XRCC1 +, DNA-PK +/XRCC1 + and ATR +/XRCC1 + tumours had the worst survival compared to ATM-/XRCC1-, DNA-PK-/XRCC1- and ATR-/XRCC1- tumours in our study." (PMID 26674120, 2014). "The results indicate a downregulation of OGG1 and an upregulation of XRCC1 expression in tumor tissue." (PMID 25268610, 2014). "In contrast to OGG1, XRCC1 showed significantly enhanced expression levels in the tumor samples, as well as in all clinical, histopathological data." (PMID 25268610, 2014). "Regarding four commonly studied polymorphic sites in ERCC1, ERCC2/XPD, and XRCC1, it was interesting to identify discordant tumor tissue/peripheral blood genotypes." (PMID 20066159, 2009). "The results suggested that besides clinical features such as tumor stage and chemotherapy or radiotherapy treatment, polymorphisms of ERCC1 Asn118Asn and XRCC1 Arg399Gln were associated with survival of patients." (PMID 20003463, 2009). "Additionally, lactate accumulation upregulated XRCC1 lactylation at K247 site, enhancing DNA repair in glioblastoma and promoting tumor cell resistance to radiotherapy and chemotherapy." (PMID 39925738, 2025). "In certain tumors, XRCC1 may play a role in modulating the tumor immune landscape by regulating the expression of immune checkpoint genes." (PMID 38217545, 2024). "Subsequently, we investigated the correlation between XRCC1 expression status and immune cell markers in LGG through the TIMER database, involving B cell, CD8+ T cells, M1/M2 macrophages, tumor-associated macrophages (TAM), neutrophils, Natural killer cell, dendritic cells." (PMID 38217545, 2024). "Therefore, it is likely that XRCC1 contributes to the poor prognosis of tumor patients by promoting DNA repair and reducing the sensitivity of tumors to chemotherapy and radiotherapy." (PMID 38217545, 2024).
tumor (continued). "Beta-COP, NID-1, and XRCC1 could be considered tumor-promoters playing a role mainly in the part of the tumor that invades and progresses into the internal tissues of the colon, and from which CRC cells migrate, mature and metastasize." (PMID 39195201, 2024). "ABCB1, ABCC1\2\3, ABCG2, ERCC1, XRCC1\2 can induce tumor chemo-resistance and radio-resistance." (PMID 37283789, 2023). "Mechanistically, XRCC1 inhibits tumour cell invasion and metastasis by regulating the expression of tissue inhibitors of matrix metalloproteinase-2 (TIMP-2) and TIMP-1, leading to the suppression of the expression of metastasis-related markers matrix metalloproteinase-2 (MMP-2) and MMP-9." (PMID 37679817, 2023). "This suggests that inhibiting the recruitment of XRCC1 to DNA lesions, or disrupting the interaction of XRCC1 with other repair enzymes, may be a feasible strategy for tumor therapy." (PMID 36497058, 2022). "This is mitigated to a certain extent by non−specific DNA repair systems; therefore, high XRCC1 expression levels may increase the DNA repair capacity of tumor cells, leading to an increased tolerance to DNA damage induced by radiochemotherapy." (PMID 34094945, 2021). "We, therefore, hypothesized that XRCC1 lack would significantly increase β-lap-induced DNA damage in a tumor-selective manner that in turn decrease β-lap uptake." (PMID 34789190, 2021). "Similarly, OS was poor in patients whose tumours had high LIG1/high XRCC1 compared to patients whose tumours had low LIG1/low XRCC1 co-expression." (PMID 34373746, 2021). "However, gender, primary tumour location, and the XRCC1-rs25487, ERCC1-rs11615, ERCC2-rs238406, and ERCC2-rs13181 polymorphisms were not statistically associated with 5-year OS (p’s > 0.05)." (PMID 32397974, 2020). "In addition, patients with the XRCC1 (CC, GC) genotypes had significantly higher number and larger size of tumor foci and significantly higher Child Pugh grades." (PMID 32334466, 2020). "For example, upregulation of XRCC1 suppressed tumor migration and invasion in glioma." (PMID 32185826, 2020). "Intriguingly, downregulation of XRCC1 has been observed in a wide range of tumour types." (PMID 29568385, 2018). "The phenotypical changes induced in normal fibroblasts by XRCC1 depletion support the idea that BER impairment could accelerate accumulation of DNA strand breaks in a pro-inflammatory tumour microenvironment." (PMID 29568385, 2018). "The phenotype observed upon XRCC1 depletion suggests that, similarly to CAFs, XRCC1 KD cells might have tumour promoting properties." (PMID 29568385, 2018). "Several key repair genes play important roles in BER pathway, such as the X-ray repair cross-complementing 1 (XRCC1), 8-oxoguanine DNA glycosylase (OGG1), and apurinic/apyrimidinic endonuclease 1 (APEX1) genes, which are associated with human tumor susceptibility and radiation toxicity." (PMID 29108254, 2017). "In addition, adjuvant platinum-based chemotherapy significantly provides an improved survival benefit in patients with reduced XRCC1 expression in gastric tumoral tissues." (PMID 29117108, 2017). "We further characterized the functions of IRF9 and XRCC1 in tumor development." (PMID 27421136, 2016). "This study was the first to detect the prognostic roles and synergistic effects of JWA/XRCC1/BRCA1 mRNA expression in paraffin-embedded tumor tissues on molecular staging for personalized therapy of advanced ESCC who received cisplatin- or docetaxel-based treatments." (PMID 25925371, 2015). "Among the five additional genotypes analyzed, two genetic variations in the XRCC1 (c.1196G>A, rs25487) and MDR1 (c.3435C>T, rs1045642) genes displayed a trend supportive of their potential association with tumor response (p = 0.050 and 0.056, respectively, Fisher’s exact test)." (PMID 25232828, 2014). "In this meta-analysis, there was not any evidence for an association nor an ethnic difference between the XRCC1 194 and 399 polymorphisms and tumor response in all patients." (PMID 24465544, 2014).